PSMA6 (proteasome 20S subunit alpha 6)
Description:
Component of the 20S core proteasome complex involved in the proteolytic degradation of most intracellular proteins. This complex plays numerous essential roles within the cell by associating with different regulatory particles. Associated with two 19S regulatory particles, forms the 26S proteasome and thus participates in the ATP-dependent degradation of ubiquitinated proteins. The 26S proteasome plays a key role in the maintenance of protein homeostasis by removing misfolded or damaged proteins that could impair cellular functions, and by removing proteins whose functions are no longer required. Associated with the PA200 or PA28, the 20S proteasome mediates ubiquitin-independent protein degradation. This type of proteolysis is required in several pathways including spermatogenesis (20S-PA200 complex) or generation of a subset of MHC class I-presented antigenic peptides (20S-PA28 complex).
Synonyms: p27K; PROS27; IOTA; MGC22756; MGC2333; MGC23846
Tractability: Small molecule: an approved drug acts on it; a structure with a bound ligand is known; a high-quality ligand is known; it belongs to a druggable protein family. PROTAC: ubiquitination databases record sites on it; its protein half-life has been measured; a small molecule that binds it is known.
Gene: Protein-coding gene on chromosome 14 (35,278,633 to 35,318,734, forward strand). Ensembl gene ENSG00000100902.
Subcellular location: Cytoplasm; Nucleus
Subcellular location (Human Protein Atlas): Nucleoplasm; Calyx; Connecting piece; Cytosol; End piece; Flagellar centriole; Mid piece; Perinuclear theca; Primary cilium; Primary cilium tip
Pathways (Reactome):
Immune System: AMPK-induced ERAD and lysosome mediated degradation of PD-L1(CD274); Activation of NF-kappaB in B cells; Antigen processing: Ub, ATP-independent proteasomal degradation; Antigen processing: Ubiquitination & Proteasome degradation; CLEC7A (Dectin-1) signaling; Cross-presentation of soluble exogenous antigens (endosomes); Dectin-1 mediated noncanonical NF-kB signaling; Downstream TCR signaling; ER-Phagosome pathway; FCERI mediated NF-kB activation; GSK3B-mediated proteasomal degradation of PD-L1(CD274); Interleukin-1 signaling; NIK-->noncanonical NF-kB signaling; SPOP-mediated proteasomal degradation of PD-L1(CD274); TNFR2 non-canonical NF-kB pathway
Cell Cycle: APC/C:Cdc20 mediated degradation of Securin; APC/C:Cdh1 mediated degradation of Cdc20 and other APC/C:Cdh1 targeted proteins in late mitosis/early G1; Autodegradation of Cdh1 by Cdh1:APC/C; Autodegradation of the E3 ubiquitin ligase COP1; Cdc20:Phospho-APC/C mediated degradation of Cyclin A; FBXL7 down-regulates AURKA during mitotic entry and in early mitosis; G2/M Checkpoints; SCF(Skp2)-mediated degradation of p27/p21; SCF-beta-TrCP mediated degradation of Emi1; Separation of Sister Chromatids; The role of GTSE1 in G2/M progression after G2 checkpoint; Ubiquitin-Mediated Degradation of Phosphorylated Cdc25A; Ubiquitin-dependent degradation of Cyclin D
Signal Transduction: Asymmetric localization of PCP proteins; Degradation of AXIN; Degradation of DVL; Degradation of GLI1 by the proteasome; Degradation of GLI2 by the proteasome; Degradation of beta-catenin by the destruction complex; GLI3 is processed to GLI3R by the proteasome; Hedgehog 'on' state; Hedgehog ligand biogenesis; MAPK6/MAPK4 signaling; Negative regulation of NOTCH4 signaling; Regulation of PTEN stability and activity
and 28 more pathways
Gene Ontology:
Molecular function: NF-kappaB binding; protein binding; RNA binding; structural constituent of proteasome; endopeptidase activity; purine ribonucleoside triphosphate binding
Biological process: positive regulation of canonical NF-kappaB signal transduction; proteasomal protein catabolic process; proteasome-mediated ubiquitin-dependent protein catabolic process; protein catabolic process; regulation of inflammatory response; regulation of proteasomal protein catabolic process; response to oxidative stress; apoptotic process; CD8-positive, alpha-beta T cell differentiation; CD8-positive, alpha-beta T cell homeostasis; cellular response to type I interferon; DNA damage response; DNA repair; flagellated sperm motility; immune system process; meiotic cell cycle; negative regulation of regulatory T cell differentiation; positive regulation of interleukin-2 production; positive regulation of tumor necrosis factor production; positive regulation of type II interferon production; proteasomal ubiquitin-independent protein catabolic process; regulation of G1/S transition of mitotic cell cycle; response to type II interferon; spermatogenesis; T-helper 1 cell differentiation; and 3 more
Cellular component: ciliary tip; cytoplasm; extracellular exosome; nucleoplasm; nucleus; proteasome complex; proteasome core complex; proteasome core complex, alpha-subunit complex; ribosome; sperm end piece; cytosol; myofibril; nuclear matrix; P-body; proteasome storage granule; sarcomere; spermatoproteasome complex; synaptic vesicle
Genetic constraint (gnomAD): Loss-of-function variants: 0 observed, 24.36 expected, observed/expected ratio (o/e) 0, 90% interval 0 to 0.12. The upper end of that interval is the gene's LOEUF score, 0.12, which puts it in group 1 of 6, group 1 being the genes least tolerant of losing a copy. Missense variants: 143 observed, 257.47 expected, observed/expected ratio (o/e) 0.56, 90% interval 0.48 to 0.64. Synonymous variants: 76 observed, 87.02 expected, observed/expected ratio (o/e) 0.87, 90% interval 0.73 to 1.06.
Homologues: Orthologues: chimpanzee PSMA6 (100% identical), macaque PSMA6 (100% identical), pig PSMA6 (100% identical), guinea pig PSMA6 (99% identical), mouse Psma6 (99% identical), tropical clawed frog psma6 (93% identical), zebrafish psma6b (91% identical), rabbit PSMA6 (90% identical), rat Psma6 (90% identical), zebrafish psma6a (90% identical), Drosophila melanogaster Prosalpha1 (67% identical), Drosophila melanogaster Prosalpha1R (67% identical), and 2 more. Paralogues in human: PSMA2 (35% identical), PSMA4 (35% identical), PSMA7 (33% identical), PSMA3 (30% identical), PSMA8 (30% identical), PSMA1 (27% identical), PSMA5 (26% identical), PSMB7 (20% identical), PSMB10 (18% identical), PSMB9 (17% identical), PSMB3 (16% identical), PSMB2 (15% identical), and 6 more.
Diseases named in the same sentence as PSMA6 in open-access papers:
PSMA6 is named in the same sentence as 62 diseases in open-access papers, as found by Europe PMC text mining. Sharing a sentence is not in itself a finding about the gene and the disease. The quoted sentences say what the papers report.
myocardial infarction (9 papers, 2013 to 2025). Gross necrosis of the myocardium, as a result of interruption of the blood supply to the area, as in coronary thrombosis. "The G2/M phase cell cycle arrest or apoptosis caused by low PSMA6 expression makes it a promising gene for myocardial infarction research and lung cancer treatment." (PMID 40507774, 2025). "The variants c.501G>C on OLR1 and c.-8C>G on PSMA6 were previously associated with myocardial infarction." (PMID 33466296, 2021). "The functional −8 G/C polymorphism in PSMA6 gene was earlier reported to be associated with several human diseases—type 2 diabetes, myocardial infarction and coronary artery disease." (PMID 27671905, 2016). "The 5′ untranslated region of PSMA6 gene contains a single nucleotide polymorphism (SNP) −8 C/G, associated with diabetes, myocardial infarction and coronary artery disease." (PMID 27671905, 2016). "One polymorphism in the proteasome gene PSMA6 (−8C/G) is associated with three different diseases: type 2 diabetes, myocardial infarction, and coronary artery disease." (PMID 24490108, 2013). "In addition, haplotypes in the chromosomal region encompassing KIAA0391 and PSMA6 have been linked to coronary artery disease and myocardial infarction." (PMID 35665255, 2022). "This parallels myocardial infarction research where PSMA6 modulates NF-κB-dependent inflammation via ubiquitination pathways." (PMID 40507774, 2025). "Several studies have reported that PSMA6 has a possible role in DM complications, such as myocardial infarction and nephropathy." (PMID 33406707, 2021). "The location of the PSMA6 gene occurs in a region containing microsatellites that have been implicated in coronary artery disease (CAD), type 2 diabetes mellitus (T2DM), Grave’s disease, asthma, ankylosing spondylitis, and myocardial infarction." (PMID 33193718, 2020).
breast carcinoma (6 papers, 2017 to 2025). "In the present study, we found that high expression of PSMA1-4 and PSMA6-7 was significantly associated with worse prognosis in breast cancer, while PSMA5 was related to better OS, RFS and DMFS." (PMID 27966459, 2017). "High-expressed PSMA family genes (e.g., PSMA2, PSMA3, PSMA4, PSMA6, and PSMA7) in breast cancer tissues are reported to be linked to a poor OS of the cancer, but higher levels of PSMA5 and PSMA8 are indicative of better clinical outcomes." (PMID 41141246, 2025). "PSMA2, PSMA3, PSMA4, PSMA6, and PSMA7 showed high expression levels, which were correlated with poor survival of breast cancer patients." (PMID 36424389, 2022). "Furthermore, PSMA2, PSMA3, PSMA4, PSMA6, and PSMA7 showed high expression levels, which were correlated with poor survival of breast cancer patients." (PMID 34943457, 2021).
coronary artery disease (5 papers, 2013 to 2022). "In particular, cg18680181 is located in the body of KIAA0391, which forms an evolutionarily conserved cluster with PSMA6 and has been reported to predispose individuals to coronary artery disease." (PMID 35665255, 2022). "In the Chinese population, the PSMA6 rs1048990 CG + GG genotype and G allele were protective factors for coronary heart disease." (PMID 27671905, 2016). "The location of the PSMA6 gene occurs in a region containing microsatellites that have been implicated in coronary artery disease (CAD), type 2 diabetes mellitus (T2DM), and Grave's disease." (PMID 24490108, 2013).
lung carcinoma (5 papers, 2017 to 2022). "In a lung cancer study, the expression of PSMA6 was up-regulated, and knocking out PSMA6 could induce lung cancer tumor cell apoptosis or the cell cycle to enter the arrest phase." (PMID 33193718, 2020). "Additionally and in support of PSMA6’s affect in PDAC cells, PSMA6 also has a similar phenotype in lung cancer and is also dispensable in normal lung tissue." (PMID 30898113, 2019). "Three other drugs (SJ‐172550 for MDM4, nutlin‐3 for MDM2/MDM4, and carfilzomib for PSMA6 and PSMB6) showed improved IC50 values when used as a monotherapy but increased efficacy when used in combination with erlotinib on NCI‐H820 lung cancer cell lines." (PMID 33188726, 2021). "In lung cancer, PSMA1-2, PSMA4 and PSMA5 were correlated with better prognosis, whereas PSMA6 and PSMA7 predicted worse survival outcomes." (PMID 27966459, 2017). "On the contrary, high PSMA6 expression was associated with worse OS (HR = 1.33; 95% CI: 0.1.17–1.51; p < 0.001) and FP (HR = 1.37; 95% CI: 1.13–1.66; p = 0.001) but not PPS for lung cancer patients." (PMID 27966459, 2017).
asthma (4 papers, 2012 to 2025). "Specifically, WGCNA highlighted the MEblack module (741 genes), enriched in proteostasis regulators (e.g., POMP, PSMA6) and immune signaling components, as a key driver of asthma pathogenesis." (PMID 41403444, 2025). "The results identified MEblack as a cluster containing 741 asthma-related core genes, including POMP, GUSBL2, RBM39, PSMA6, RFX1, TCEB1, PSMD6, and others." (PMID 41403444, 2025).
diabetes (4 papers, 2013 to 2020). "The PSMA6 gene has been shown to harbor single nucleotide polymorphism, including a 5’-UTR 8 C/G, associated with diabetes, and that PSMA6 polymorphism might be a protective factor for ESRD." (PMID 30287505, 2018). "Interestingly, the same −8C > G variant of PSMA6 gene that was associated with CAD was found to be associated with T2DM and diabetes-related metabolic traits in two Chinese populations." (PMID 24490108, 2013).
gastric cancer (4 papers, 2016 to 2023). A primary or metastatic malignant neoplasm involving the stomach. "For example, exosomal PSMA3 and PSMA6 are explicitly enriched in serum during metastatic gastric cancer, but not primary gastric cancer, thus being a potential biomarker for gastric cancer metastasis." (PMID 34109113, 2021). "PSMA3 and PSMA6 were found to be remarkably higher in serum sEVs of patients with metastatic gastric cancer (mGC) than in healthy controls and patients with early GC." (PMID 36674743, 2023). "Consistent with this, proteasome subunit PSMA6 and PSMB8 were more highly expressed in gastric cancer patients with a poor prognosis compared with patients with a good prognosis." (PMID 26894977, 2016).
lung adenocarcinoma (4 papers, 2017 to 2024). A carcinoma that arises from the lung and is characterized by the presence of malignant glandular epithelial cells. "Two studies of Yamagata showed that the expression level of PSMA6 was significantly elevated in lung adenocarcinoma and large cell lung carcinoma compared to normal lung tissues." (PMID 27966459, 2017). "This analyses identified four proteins—Pdhx, Psma6, Ruvbl1, and Ywhaq—that were increased in abundance as a result of ECS exposure and also amplified in human lung adenocarcinomas." (PMID 39273313, 2024). "Seven other 26S/20S proteasome subunits were isolated (q < 0.05; PSMD12, PSMB4, PSMA6, PSMB6, PSMC1, PSMD3, and PSMB3), illuminating the importance of the 26/20S proteasome integrity in lung adenocarcinoma genome maintenance." (PMID 34070461, 2021).
type 2 diabetes (4 papers, 2013 to 2025). "In addition, the rs2277460 SNP in the PSMA6 (α1) gene has been linked to T1DM as well as other metabolic disorders, including type 2 diabetes mellitus (T2DM) and coronary artery disease." (PMID 41441015, 2025).
COVID-19 (3 papers, 2022 to 2024). A disease caused by infection with severe acute respiratory syndrome coronavirus 2. "We observed that genes encoding HLA class 1 (HLA-E, PSMA-6, TAP1, IFI30) were enriched in COVID-19 ECs." (PMID 37029220, 2023). "Among the low-frequency variants extracted, we identified some genes associated with either severity or protection from severe COVID-19 that are linked to the CFTR pathway (e.g., PSMA6) as well as specific genes involved in the immune response (e.g., NOD2)." (PMID 34889978, 2022). "Multiple proteasome subunits (e.g., PSMA1, PSMA5, PSMA6, PSMA7, and PSMB1) were upregulated in COVID-19 patients, especially during the acute phase of disease, potentially contributing to the dysregulation of proteasome activity." (PMID 38965561, 2024).
ischemic stroke (3 papers, 2013 to 2020). A stroke disorder caused by obstruction of blood flow to the brain, due to thrombotic (local blood clot formation) or embolic (due to a blood clot or other material traveling from another site) event. "The PSMA6 −8C > G (SNP rs1048990) was found to have a protective association with ischemic stroke in both Caucasians and African Americans (i.e., decreased risk of ischemic stroke)." (PMID 24490108, 2013). "Proteasome subunit type 6 (PSMA6) gene polymorphisms are associated with susceptibility to ischemic stroke, while PSMA6 (-C8G) gene polymorphism may play a protective role with the susceptibility of ischemic stroke." (PMID 32089771, 2020). "In both studies, the authors found a protective effect of the PSMA6 rs1048990 SNP on overall ischemic stroke, with OR 0.79, p = 0.037 and OR 0.80, p = 0.036, respectively." (PMID 27671905, 2016).
melanoma (3 papers, 2017 to 2025). A malignant, usually aggressive tumor composed of atypical, neoplastic melanocytes. "With respect to melanoma, the mRNA expression levels of PSMA1, PSMA3, PSMA5 and PSMA6 were upregulated in melanoma compared with normal tissues according to Haqq's dataset." (PMID 27966459, 2017).
Nephropathy (3 papers, 2018 to 2021). A nonspecific term referring to disease or damage of the kidneys. "Similar to our results, the PSMA6 CC genotype was previously demonstrated to be more common in the patients with the endstage of renal disease than in controls (80% vs. 58%, respectively), which suggested a protective role of the G allele." (PMID 34575036, 2021). "Exogenous manipulation of miR-4490 levels modulated expression of PSMA6, indicating that miR-4490 can be tested as a biomarker for nephropathy in diabetic patients." (PMID 30287505, 2018). "Our results show that exogenous manipulation of miR-4490 levels can modulate expression of PSMA6, indicating that miR-4490 can be tested as a potential biomarker for nephropathy in diabetic patients." (PMID 30287505, 2018).
diabetic kidney disease (2 papers, 2018 to 2025). Progressive kidney disorder caused by vascular damage to the glomerular capillaries, in patients with diabetes mellitus. "The PSMA6 rs1048990G allele was linked to increased prevalence of diabetic kidney disease (DKD; OR = 1.75, 95% CI 1.02–2.99; p = 0.042), and the PSMD3 rs3087852A allele was associated with lower urinary albumin excretion." (PMID 41441015, 2025). "We thus initially determined PSMA6 protein expression in tissue specimens obtained from patients with diabetic nephropathy and healthy controls." (PMID 30287505, 2018). "Using a rat model of diabetic nephropathy it was observed that expression of proteasome subunit-α type-6 protein (PSMA6) is suppressed in renal cortex of nephropathic kidney." (PMID 30287505, 2018). "Our results show that PSMA6 protein is down-regulated in patients with diabetic nephropathy compared with healthy control." (PMID 30287505, 2018). "It has been previously shown using a rat model of diabetic nephropathy that PSMA6 protein expression is suppressed in the renal cortex." (PMID 30287505, 2018). "Patients with diabetic nephropathy had undetectable levels of PSMA6 compared with healthy controls." (PMID 30287505, 2018). "Using the NRK-52E cell line cultured under high glucose condition as an in vitro model of diabetic nephropathy, we show that loss of PSMA6 protein expression occured independent of changes the in PSMA6 mRNA expression." (PMID 30287505, 2018). "However, regulatory mechanisms underlying PSMA6 protein expression in diabetic nephropathy are not completely defined." (PMID 30287505, 2018). "Our results show that miRNA-4490 is up-regulated in an in vitro model of diabetic nephropathy, NRK-52E cells cultured under high glucose for a prolonged period, and targets PSMA6 for post-transcriptional silencing." (PMID 30287505, 2018). "Here, using an in vitro model of diabetic nephropathy, NRK-52E cells maintained under high glucose conditions, we found that PSMA6 gene expression is not regulated at the mRNA level, but at the post-transcriptional level." (PMID 30287505, 2018).
Graves disease (2 papers, 2013 to 2020). Graves' disease is an autoimmune disorder that leads to overactivity of the thyroid gland (hyperthyroidism).It is caused by an abnormal immune system response that causes the thyroid gland to produce too much thyroid hormones. "A 270 kb chromosome region (14q13.2-14q13) containing PSMA6 was analyzed for polymorphisms and associations of five microsatellite repeats in 50 Latvian patients with Graves' disease and 116 controls with Graves' disease." (PMID 24490108, 2013). "Further analysis is needed to confirm the importance of PSMA6 in Graves' disease." (PMID 24490108, 2013).
hepatocellular carcinoma (2 papers, 2015 to 2017). A malignant tumor that arises from hepatocytes. "Upregulation of PSMA6, PSMB4, PSMC2 and PSMD12 was also observed in hepatocellular carcinomas in p21-HBx transgenic mice." (PMID 27966459, 2017).
Multiple Myeloma (2 papers, 2020 to 2021). "PSMA5 was significantly upregulated in endometrial cancer, while PSMA6 was significantly upregulated in multiple myeloma patients and pancreatic ductal carcinoma cell models." (PMID 34943457, 2021).
pancreatic ductal carcinoma (2 papers, 2019 to 2021). "Spheroid formation assays and flow cytometry analysis showed that PSMA6 is critical for survival in many pancreatic ductal carcinoma cell models." (PMID 30898113, 2019).